IL27 (interleukin 27)
Diseases named in the same sentence as IL27 in open-access papers (continued):
Sharing a sentence is not in itself a finding about the gene and the disease.
Sepsis (continued). "Cytokines known to activate the adaptive immune system were generally higher in sepsis compared to the healthy cohort, including RANTES (p=0.01), G-CSF (p<0.0001), M-CSF (p<0.0001), IL-6 (p<0.0001), IL-8 (p<0.0001), IL-27 (p<0.0001), and MIP-1β (p<0.0001)." (PMID 39935482, 2025). "IL-27 has been shown to influence innate immunity and macrophage polarization, including inhibition of the Nrf2/HO1 signaling pathway in sepsis-induced ARDS models, promoting M1 polarization and inhibiting M2 polarization." (PMID 41024268, 2025). "Regarding IL-27, the SS group showed lower levels of circulating IL-27 than the ICU and sepsis groups." (PMID 35327327, 2022). "Thus, IL-27 may develop into a biological marker in diagnosing sepsis in the future." (PMID 33954170, 2021). "Thus, IL-27 may be a more useful diagnostic biomarker in patients with sepsis who were not yet an adult." (PMID 33954170, 2021). "When patients with infection and patients with severe sepsis on ICU admission were compared, IL2, IL7, IL23, IFNγ, and TNFα gene expression was lower in patients with sepsis, while IL-27 gene expression was similar in these two groups." (PMID 23935244, 2013). "Serum concentrations of interleukin-27 (IL-27) and procalcitonin (PCT) were compared between 101 patients with SIRS and 130 patients with sepsis." (PMID 23107287, 2012). "Additionally, the peritoneal lavage of all sepsis groups exhibited increased PGE2, IL-27, IL-1β, and IL-12p70 levels." (PMID 39281680, 2024). "In summary, we present novel findings that suggest a transcriptional reprogramming of the host response in splenic tissue in the absence of IL-27 signaling during E.coli-induced infection in a neonatal murine sepsis model." (PMID 36891292, 2023). "To date, there has been no meta-analysis on the effectiveness of IL-27 as a biological marker for sepsis diagnosis." (PMID 33954170, 2021). "Many studies have shown the efficacy of interleukin-27 (IL-27) for the differential diagnosis of sepsis and nonsepsis." (PMID 33954170, 2021). "In murine models of polymicrobial sepsis induced by CLP, and endotoxic shock induced by lipopolysaccharide (LPS), blockade of IL-27 with neutralizing anti-IL-27p28 antibodies decreased inflammatory cytokine levels (IL-1β, IL-17 and IFN-γ), and improved the survival rate." (PMID 34079555, 2021). "Further studies with a large sample size are needed to be designed to reduce the heterogeneity in the analysis of the utility of IL-27 for discrimination between sepsis and nonsepsis." (PMID 33954170, 2021). "Furthermore, IL-27 expression in patients with sepsis carrying the rs153109 AA genotype significantly increased compared to that of the GA/GG genotype carriers, suggesting that this SNP might be involved in the pathogenesis of sepsis by altering its gene transcription." (PMID 30268141, 2018). "The rationale for investigating IL-27 is based on the observation that EBI3 had the highest predictive strength for bacterial infection of all genes differentially regulated between patients with SIRS and patients with sepsis." (PMID 23107287, 2012). "Enhanced understanding of the mechanisms by which the absence of IL-27 signaling in neonates promotes resistance to sepsis may lead to development of novel therapeutic approaches." (PMID 40977737, 2025). "However, in the absence of IL-27 signaling in adult mouse models of sepsis (WSX-1 knockout), increased neutrophil levels and corresponding reactive oxygen species (ROS) were demonstrated, consistent with reduced bacterial burdens." (PMID 32802395, 2020). "In this study, however, co-infection with other microbes such as those seen in the HIV-infected patients without malaria (e.g., tuberculosis, bacterial pneumonia and sepsis), did not seem to influence IL-27 levels to the same degree as co-infection with falciparum malaria." (PMID 31964363, 2020).
Sepsis (continued). "It is currently unknown how much IL-33 signaling changes during sepsis in the absence of IL-27 signaling and therefore might lower the efficacy of IL-27 blockade in improving long term survival in sepsis patients who receive no further interventions." (PMID 31507598, 2019). "While many reviews have discussed the therapeutic potential for targeting IL-17, IL-27, and IL-33 during sepsis, none have considered the effect that treatment targeting only one of these cytokines may have on the others." (PMID 31507598, 2019). "Our results infer that the genetic effect of the − 964 A-to-G variation might make a real difference following inflammatory stimuli or stress, which also suggests that the IL-27 rs153109 SNP influences the sepsis severity rather than the onset of sepsis." (PMID 30268141, 2018). "However, in contrast to the findings in sepsis, the increased expression of IL-27 in COPD was accompanied with an amplified, uncontrolled chronic inflammatory response, suggesting a pro-inflammatory activity of IL-27 in this context." (PMID 27994590, 2016). "Serum IL-27 protein levels ≥5 ng/ml, obtained within the first 24 hours of meeting clinical criteria for SIRS/sepsis, had a high specificity and a high positive predictive value for predicting bacterial infection in our cohort of more than 200 critically ill patients with SIRS or sepsis." (PMID 23107287, 2012). "Previously, we and others have described heterogeneous populations of myeloid cells as IL-27 producers; however, a detailed in vivo analysis of paired single-cell phenotypic and transcriptional data specifically in neonatal mice during sepsis has not been reported." (PMID 40682363, 2025). "Thus, only 18 of 100 patients with negative IL-27 results may ultimately be diagnosed with sepsis." (PMID 33954170, 2021). "Furthermore, since survival from sepsis in murine neonates does not depend on an intact adaptive immune system, the improved innate immune cell-mediated clearance of bacteria in the absence of IL-27 is likely critical to the improved mortality in those neonatal pups." (PMID 31818960, 2020).
viral infection (50 papers, 2013 to 2025). "IL-27 signaling contributes to both host defense and lung injury, as it attenuates lung pathology following viral infection, but enhances susceptibility to secondary bacterial." (PMID 25651926, 2015). "Here, we utilized trophoblast organoids (TO) derived from primary human placentas and a mouse model of congenital viral infection to uncover the functional role of IL-27 signaling during pregnancy." (PMID 40502752, 2025). "Given the functional IL-27 signaling circuit in TOs and its known capacity to restrict viral infection in other contexts, we next sought to define IL-27-mediated gene expression changes in TOs." (PMID 40502752, 2025). "In vitro and in vivo evidence have demonstrated that IL-27 directly enhances IFN production in response to viral infections in various cell types." (PMID 38720890, 2024). "During viral infections, macrophages are key components of innate immunity that produce interferons (IFNs) and IL27." (PMID 38932287, 2024). "The regulatory functions of IL-27 in the setting of viral infection involves both IL-10 dependent and independent mechanisms." (PMID 38966644, 2024). "Here, we discuss the latest advancements in the role of IL-27 in several viral infection models of human disease." (PMID 38966644, 2024). "IL-27 antiviral properties against several human viruses have highlighted its potential therapeutic use for the treatment of human viral infections." (PMID 38966644, 2024). "IL-27 signaling modulates several immune cells and there is a need to better define its temporal expression and its cell sources during viral infections." (PMID 38966644, 2024). "In this regard, it has been described that the IL-27 pathway participates in the response to viral infections through IFN-I-dependent and -independent mechanisms, in addition to triggering the production of different inflammatory mediators." (PMID 39637135, 2024). "To our knowledge, we are the first to report the induction of expression of these TRIMs in response to IL27 treatment within the context of a viral infection." (PMID 38932287, 2024). "In the present manuscript, we will discuss the role of IL-27 in T cell mediated immunity in the setting of viral infection." (PMID 38966644, 2024). "The early induction of Th1 cytokines such as IL-1β and IL-18 is protective to infected hosts by promoting CD8+ T-cell activity and antibody responses, and IL-27 is effective against viral infections by decreasing immunopathology and increasing survival." (PMID 39066362, 2024). "Some members such as IL-27 and IL-35 even exhibit dual effects, i.e., pro- and anti-inflammatory responses in the course of virus infections." (PMID 37108513, 2023). "Given the importance of sustained antiviral immunity in controlling persistent viral infections, here, we sought to dissect the precise roles of IL-6 and IL-27 in the regulation of gp130-mediated responses." (PMID 37583704, 2023). "In terms of anti-inflammatory reactions, IL-27 signals the formation of regulatory T cells (Treg) which in turn secrete IL-35 to control the scale of inflammatory response that takes place during virus infections." (PMID 37108513, 2023). "IL-27 indeed has a broad spectrum of functions during a virus infection; whilst regulating the host immune response to prevent prolonged, damaging inflammation, it also functions to inhibit virus replication." (PMID 37108513, 2023). "Our results suggest that CHIKV promotes the expression of IL27 subunits and activates the IL27-dependent signaling following viral infection." (PMID 35223841, 2022). "IL-27 marks early T-cellular responses, providing the polarization and maturation of such cells; as T cytotoxic lymphocytes are the main effectors against viral infections, IL-27 is an important factor of adaptive immunity." (PMID 36430621, 2022). "In vitro and clinical studies show that IL-27 can interact with IL-6 to form a complex during viral infection." (PMID 35634328, 2022).
viral infection (continued). "The vast array of responses influenced by IL-27 relates to its ability to inhibit a variety of viral infections and makes it a promising therapeutic and vaccine adjuvant for existing and emerging viral threats." (PMID 35634328, 2022). "This review discusses the IFN-dependent and IFN-independent antiviral mechanisms of IL-27 and highlights the potential of IL-27 as a therapeutic cytokine for viral infection." (PMID 35634328, 2022). "The promotion of IFNγ-producing antigen-specific CD8+ T cells by IL-27 highlights the adjuvant potential of this cytokine for prophylactic measures against viral infection." (PMID 35634328, 2022). "Another way that IL-27 promotes innate immune responses during viral infection is by augmenting NK cell function." (PMID 35634328, 2022). "There are small studies on the importance of the pre- and post-activating pathway of IL-27 in viral infections." (PMID 34996392, 2022). "A growing body of evidence demonstrates that IL-27 signaling promotes IFNγ production by CD8+ T cells during viral infection." (PMID 35634328, 2022). "IL-27 has been shown to play an important role in stimulating the transcription of cytosolic innate immune sensors, such as Mx1, Oas1, and Oas2, during viral infection." (PMID 36678402, 2022). "Earlier we reported that CHIKV infection-induced IL27 expression; here we now explore if the virus infection also triggers the expression of components of IL27 signaling." (PMID 35223841, 2022). "Accumulating evidence supports the proposal that IL-27 enhances ISG transcription during viral infection by augmenting the production of IFNs." (PMID 35634328, 2022). "Now, there are studies which pointed out that IL-27 can inhibit viral infection by activating STAT1/3 and CXCL9/10." (PMID 35785034, 2022). "IL-27 produced as a consequence of type I IFN signaling has also been shown to influence T cell responses during viral infection." (PMID 35634328, 2022). "In particular, it is a major signal transmitter of IFN-γ, an important mediator of immune responses and inflammation, and its deficiency results in susceptibility to viral diseases and impaired responses to IFN-γ and IL-27." (PMID 34208434, 2021). "This susceptibility was not due to defects in viral clearance but was associated with more severe pathology, suggesting that IL-30 or IL-27 is critical in limiting pathology during viral infection." (PMID 34045653, 2021). "The immunoregulatory cytokine IL-27 has been shown to protect against lung inflammatory damage during the course of viral infections." (PMID 32660087, 2020). "In contrast, when IL-27 was administered early after virus infection, viral clearance was impaired and increased immunopathology ensued." (PMID 32802395, 2020). "Recent studies highlighted the role of IL-27 in the protection against lung inflammatory damage during the course of viral infections." (PMID 33133080, 2020). "IL-27 strongly induced STAT1-dependent pathways and weakly induced STAT3-dependent pathways implicated in flaring up the viral infection and HCC progression in liver viral infection, suggesting the probable use of IL-27 as a safe treatment in viral hepatitis." (PMID 33381596, 2020). "IL-27 can also suppress virus infection, thus it is considered as a potential therapeutic target in cancer immunotherapy, autoimmune, and infectious diseases." (PMID 31835347, 2019). "IL-27 has previously been shown to inhibit various virus infections such as human immunodeficiency virus (HIV) type-1, HIV-type-2, hepatitis B virus (HBV), herpes simplex virus type 1 (HSV-1), and influenza A." (PMID 31835347, 2019). "IL-27’s role in the immune response to viral infection seems to be more context dependent with varying outcomes on viral control and immune pathology depending on the class of virus." (PMID 30044874, 2018).
viral infection (continued). "Although this immune regulatory role of IL-27 restricts pathogen control in models of parasitic or bacterial infection, the outcome of IL-27 mediated immune regulation seems more variable in the context of viral infection." (PMID 30044874, 2018). "Removal of either IL-6 or IL-27 enhances disease during viral infection, while restoration of IL-27 is sufficient to allow faster recovery." (PMID 28953978, 2017). "To determine the role of IL-27 during RSV infection, we administered IL-27 neutralising antibodies into the airways prior to viral infection." (PMID 28953978, 2017). "In turn, IL-27 production in response to viral infection was triggered by type-I interferon, a prototypic antiviral cytokine." (PMID 27926930, 2016). "Recently, the passive and active roles of IL-27 in the pathogenesis of several viral diseases have been closely examined." (PMID 27403033, 2016). "As the primary macrophage response to viral infection involves type-I IFN signaling we next directly tested the dependency of IL-27 induced expression in macrophages that are genetically ablated for either IFNβ production or type-I IFN signaling." (PMID 27926930, 2016). "CXCL-9 and CXCL-10 are STAT1-dependent inflammatory factors induced by different cell populations in response to interferons and IL-27, and their expression correlates with the induction of interferon-stimulated genes (ISGs) which promote an antiviral state to control viral infections." (PMID 40711072, 2025). "They suspected that elevated levels of IL-27 in severe SARS-CoV-2 are linked to illness recovery, possibly due to its effect on generating antiviral proteins and stimulating some immune cells that play critical roles in viral infections." (PMID 40057761, 2025). "However, the results of this study provide new insights into the function of IL-27 and the potential existence of a novel subset in macrophages resisting broad viral infection by inducing multiple ISGs in most cells." (PMID 40129989, 2025). "IL-27 signaling is involved in other pathological conditions such as atherosclerosis, non-small cell lung cancer (NSCLC) and other inflammatory diseases but the dynamics of IL-27 subunit coexpression in human tissues in the setting of health and viral infections remains scarce." (PMID 38966644, 2024). "Consequently, IFNs and IL27 play essential roles in mediating innate immunity against viral infection through activating JAK-STAT signaling and inducing ISGs." (PMID 38932287, 2024). "Additionally, it has been reported that the IL-27 pathway can induce an antiviral response during various viral infections, including SARS-CoV-2; by activating the STAT1 pathway and producing different ISGs independently of IFN-I." (PMID 39637135, 2024). "IL-27 may have a potential clinical applications in the setting of viral infections, while its antiviral effects seem broad and synergistic with Type I IFNs, its modulatory effects require further investigation in the setting of viral infections." (PMID 38966644, 2024). "Given the importance of IL-6, TNF-α, IL-12p40, IL-23, and IL-27 in aiding the immune system during viral infection and supporting viral immunity, a fermentate that can enhance these cytokines could indeed be beneficial." (PMID 39123583, 2024). "In the setting of viral infections, the role of IL-27 is not well understood." (PMID 38966644, 2024). "However, IL-27 is required to maintain virus-specific CD4 T-cell numbers after chronic viral infection but also influences IFN-I, DC, and NK cell responses early after infection." (PMID 37583704, 2023). "Additionally, NK cell production of granzyme B, a protease that kills virus-infected cells, was diminished in il27rα-/- mice and associated with reduced viral clearance, suggesting a role of IL-27 in mediating NK cell effector functions during virus infection." (PMID 35634328, 2022).